ASB13 (ankyrin repeat and SOCS box containing 13)
Description:
May be a substrate-recognition component of a SCF-like ECS (Elongin-Cullin-SOCS-box protein) E3 ubiquitin-protein ligase complex which mediates the ubiquitination and subsequent proteasomal degradation of target proteins.
Synonyms: FLJ13134; MGC19879
Tractability: PROTAC: ubiquitination databases record sites on it.
Gene: Protein-coding gene on chromosome 10 (5,638,857 to 5,666,615, reverse strand). Ensembl gene ENSG00000196372.
Subcellular location (Human Protein Atlas): Golgi apparatus; Nucleoplasm
Pathways (Reactome):
Immune System: Antigen processing: Ubiquitination & Proteasome degradation
Metabolism of proteins: Neddylation
Gene Ontology:
Molecular function: protein binding
Biological process: intracellular signal transduction; protein ubiquitination
Cellular component: cytosol
Genetic constraint (gnomAD): Loss-of-function variants: 33 observed, 26.06 expected, observed/expected ratio (o/e) 1.27, 90% interval 0.96 to 1.69. The upper end of that interval is the gene's LOEUF score, 1.69, which puts it in group 6 of 6, group 1 being the genes least tolerant of losing a copy. Missense variants: 414 observed, 372.83 expected, observed/expected ratio (o/e) 1.11, 90% interval 1.02 to 1.2. Synonymous variants: 182 observed, 161.7 expected, observed/expected ratio (o/e) 1.13, 90% interval 1 to 1.27.
Homologues: Orthologues: chimpanzee ASB13 (99% identical), macaque ASB13 (99% identical), rabbit ASB13 (99% identical), guinea pig ASB13 (98% identical), mouse Asb13 (98% identical), dog ASB13 (96% identical), rat Asb13 (93% identical), pig ASB13 (90% identical), tropical clawed frog asb13 (73% identical), zebrafish asb13b (69% identical), zebrafish asb13a.2 (62% identical), zebrafish asb13a.1 (57% identical).
Diseases named in the same sentence as ASB13 in open-access papers:
ASB13 is named in the same sentence as 6 diseases in open-access papers, as found by Europe PMC text mining. Sharing a sentence is not in itself a finding about the gene and the disease. The quoted sentences say what the papers report.
breast carcinoma (2 papers, 2023 to 2025). "Knockdown of ASB13 promotes cell migration in breast cancer cells, and ASB13 is associated with the development of acute myocardial infarction." (PMID 40244387, 2025). "A similar study suggested that ASB13 inhibits breast cancer metastasis by promoting SNAI2 degradation." (PMID 37251370, 2023).
morbid obesity (1 paper, 2025). An excess of body weight, normally defined as an individual with a body mass index greater than 35 or a body weight greater than one hundred percent of ideal body weight. "Genetic polymorphisms in ASB13 have been found to be associated with an increase in the size of the fat compartment and morbid obesity." (PMID 40665728, 2025).
Shock (1 paper, 2022). The state in which profound and widespread reduction of effective tissue perfusion leads first to reversible, and then if prolonged, to irreversible cellular injury. "We also found that, the two hub genes, ASB13 and CDCA7, were both apoptosis-related genes, suggesting that ECMO may affect the prognosis of patients through apoptosis, in the AMI complicated by cardiogenic shock." (PMID 36531699, 2022).
cancer (2 papers, 2021). A tumor composed of atypical neoplastic, often pleomorphic cells that invade other tissues. "Target genes of miR-576 (CUL3 and RAC1) have been identified to be involved in the regulation of multiple cancer-related biological pathways, and the target genes of miR-616 (ASB13 and FBXW2) have been reported to be associated with the development of other cancers." (PMID 35008363, 2021).
ASB13 also shares sentences with these, for which no sentence is quoted: acute myocardial infarction (1 paper); autoimmune disease (1).